TNF (tumor necrosis factor)
Diseases named in the same sentence as TNF in open-access papers (continued):
Sharing a sentence is not in itself a finding about the gene and the disease.
Arthritis (continued). "It has been recently reported that a combined therapy with anti-CD3 and anti-TNF leads to a long-term amelioration of established arthritis in an animal model." (PMID 24223832, 2013). "The pro-inflammatory cytokines such as IL-1β and TNF-α, produced by the activated macrophages and T cells, appear to be involved in the perpetuation of arthritis." (PMID 23971042, 2013). "Arthritis induced by antibodies to type II collagen resulted in increased levels of TNF-α, INF-γ, IL-17 and Rantes (* p < 0.05; N = 5)." (PMID 24368568, 2013). "Sustained pain also impacts the BLA as intraplantar formalin induces c-fos mRNA, arthritis increases the expression of the pro-nociceptive cytokine tumor necrosis factor α (TNF-α) and neuropathy increases cell proliferation in the BLA." (PMID 25408902, 2013). "Anti-TNF-α therapies are used in clinics currently for inflammatory bowel disease and arthritis, and serve as an attractive future solution to reduce reproductive pathologies induced by genital chlamydial infection." (PMID 23483844, 2013). "This is supported by evidence indicating that in macrophages PGE2 works in concert with IL-6 to inhibit TNF-α production in a murine arthritis/lupus model." (PMID 24025197, 2013). "IL-1β, IL-6, IL-17, and TNF are found to be elevated during the development of arthritis, and inhibition of TNF and IL-6 represent successful treatments of RA." (PMID 24286140, 2013). "Tumour necrosis factor-α (TNF-α) and interleukin-1 (IL-1) are produced by macrophages and synovial lining cells and can be found in high concentrations in arthritis." (PMID 23476804, 2013). "Osteoclast precursors are increased in the peripheral blood of TNF-Tg mice and psoriatic patients with arthritis." (PMID 23762085, 2013). "Considering the potentially detrimental effect of TNF antagonists on lupus manifestation, our data support the preferential choice of abatacept in a patient with rhupus syndrome whose arthritis is refractory to MTX." (PMID 24324510, 2013). "A significant increase (P < 0.05) in the TNF-α level was seen in the arthritis alone rats compared to controls." (PMID 23476804, 2013). "HLXL-treated rats with AA showed decreased arthritis scores as well as the levels of proinflammatory cytokines (IL-1β, IL-6, IL-17, TNF-α), chemokines (RANTES, MCP-1, MIP-1α, GRO/KC), and MMPs." (PMID 23476694, 2013). "In a rat model of arthritis, artesunate treatment significantly attenuated inflammation and cartilage damage by decreasing the levels of IL-1β, IL-17 and TNF in rat’s hind paws." (PMID 24180288, 2013). "The present work is an extension of a report on antibody response following pneumococcal vaccination using 7-valent conjugate vaccine in arthritis patients treated with TNF-inhibitors." (PMID 24286269, 2013). "It was demonstrated that electroporation of anti-TNFα siRNA resulted in inhibition of joint inflammation in collagen-induced arthritis." (PMID 24276020, 2013). "MTX was identified as a predictor of impaired positive AR in a multivariate logistic regression model, which is in accordance with our previous reports including arthritis patients treated by anti-TNF remedies." (PMID 24286269, 2013). "In this respect, TNF-α has received the most attention as one of the critical cytokines in the pathophysiology of arthritis, and is thus a major druggable target for biological agents and small molecules." (PMID 23305345, 2013). "There was a significant decrease in TNF-α levels in the plasma of the glucosamine treated group (P < 0.05) than the untreated arthritis only control group." (PMID 23476804, 2013). "Many studies are actually conducted to target IL-17 in arthritis models because of its potential synergistic effects with IL-1β, IL-6, and TNF-α in inducing cytokine expression and joint damage." (PMID 22414623, 2012). "Our data showed an increase of paw diameter, arthritis scores and inflammatory mediator levels in serum known to be involved in the RA process, such as TNFα and PGE2, in AIA rats." (PMID 23079082, 2012).
Arthritis (continued). "Very few studies to date have assessed anti- TNF-α treatment on cachexia, and only in patients with cancer or arthritis." (PMID 22708547, 2012). "Biological agents, a new category of arthritis treatments called tumor necrosis factor (TNF) inhibitors, have been developed." (PMID 23163934, 2012). "Because synovitis that produces TNF contributes to the effector phase of arthritis in both RA and PsA, TNF inhibitors are effective for both types of arthritis." (PMID 23133751, 2012). "Among the biologic agents, infliximab, which is a chimeric anti-TNF-α monoclonal IgGI antibody, is the most widely used and has been proven in many studies to control the primary IBD and associated arthritis." (PMID 22236863, 2012). "A very large number of studies have been performed investigating the importance of TNF-alpha in arthritis, especially RA." (PMID 22505941, 2012). "Serum TNFα levels were elevated in CIA mice treated with vehicle only compared to non-arthritis controls." (PMID 22812502, 2012). "IL-1β, IL-6, and TNFα are elevated in human RA synovium and have also been shown to contribute to the development of arthritis in animal models." (PMID 22414623, 2012). "Three studies are actually detectable regarding the influence of TNF-α SNPs on the anti TNF-α effects in paediatric arthritis population." (PMID 23133455, 2012). "Correspondingly, histological measures of arthritis were reduced, as was tissue expression of IL-6, IL-1β and TNF-α." (PMID 23071771, 2012). "c-Fos/AP-1 controls the expression of inflammatory cytokines including TNF-α by binding directly to AP-1 motifs in the promoter of the gene, and T-5224 treatment resolved arthritis in a mouse model." (PMID 23173923, 2012). "In RA, tumor necrosis factor (TNF) primarily contributes to the arthritis effector phase and IL-6 contributes to the arthritis priming phase." (PMID 23133751, 2012). "Anti-S100A9 and anti-TNFα treatment significantly reduced the maximum arthritis score median, from 6.8 in the isotype control-treated group to 3 and 1.4 in groups treated with anti-S100A9 and anti-TNFα, respectively." (PMID 23029038, 2012). "The antiinflammatory cytokine IL-10 plays an important role for control of excessive immunity and damage to the host during infections, and we showed that IL-10 is protective against S. aureus arthritis, at least partly by inhibition of TNF-α." (PMID 22507741, 2012). "The MK2 gene deletion protected DBA/1LacJ mice from collagen-induced arthritis due to a significantly lower LPS-induced TNF-α and IL-6 serum levels when compared with wild-type controls." (PMID 22315682, 2012). "The results demonstrated that IL-17 was the first cytokine to peak (at 12 hours after arthritis induction), followed by IL-6, TNFα, IL-1β, and IFNγ at 24 hours after the challenge." (PMID 22676339, 2012). "Prior studies have shown that macrophages derived from NMU-KO mice produced normal levels of IL-1β and TNF, critical arthritogenic cytokines in K/BxN serum-transferred arthritis and also IL-12p40 following lipopolysaccharide stimulation." (PMID 22314006, 2012). "Previous studies showed a maximum of induction 6 hours after arthritis induction but this measure was performed on synovial membrane homogenates, and consequently the measured TNF-α level addressed both transmembrane and extracellular mediators." (PMID 22414623, 2012). "In this study, we investigated the mechanism of action of BZX and its dismantled formulae in RA treatment and its effect on the IL-1 and TNF levels in a type II collagen-induced rat arthritis model." (PMID 23163934, 2012). "IL-17 activates synovial fibroblasts and macrophages to stimulate the production of IL-6 and TNFα, which lead to joint inflammation." (PMID 22768242, 2012). "Similar results were obtained in a third model of arthritis in which chronic polyarthritis is driven solely by overexpression of human TNF-alpha via a transgene." (PMID 22470501, 2012).
Arthritis (continued). "We also examined the effect of HLXL on two of the major arthritis-related cytokines (IL-1β and TNF-α) produced by the synovial tissue from the joints of arthritic mice and rats." (PMID 20981317, 2011). "Doppler-US has become an important technique for follow-up of adult arthritis after steroid injections or systemic anti-TNF." (PMID 21276257, 2011). "In this study the same parameters were assessed in patients after anti-TNF-α treatment and we found significant positive association between synovial 4-HNE expression and clinical measures of arthritis." (PMID 21787418, 2011). "This led us to conduct a preliminary analysis of anti-TNF-alpha therapy in MPS VI rats using Remicade®, the FDA-approved anti-human TNF-alpha monoclonal antibody used in arthritis and other inflammatory diseases." (PMID 21887218, 2011). "In particular, cytokines secreted from synoviocytes, such as TNF-α and IL-1, were considered major determinants in the perpetuation of arthritis." (PMID 21569552, 2011). "The treatment of murine models of arthritis with antibodies against TNF-α and IL-1 or with soluble TNF-α, receptor ameliorates or abrogates the disease." (PMID 22085488, 2011). "TNF blockers have provided the first evidence-based treatment for PsA with proven effects on arthritis, skin disease, enthesitis, dactylitis, and spinal disease." (PMID 21624183, 2011). "Targeting of the inflammatory cytokine TNF-α by biologic agents, such as Adalimumab, has been the most beneficial treatment strategy to date for patients with arthritis." (PMID 21345222, 2011). "TNF transgenic (Tg) mice with asymmetric knee arthritis were identified by contrast-enhanced (CE) magnetic resonance imaging (MRI), and PLN were phenotyped as "expanding" or "collapsed" using LNcap threshold = 30 (Arbitrary Unit (AU))." (PMID 21884592, 2011). "Progranulin and Atsttrin prevented inflammation in multiple arthritis mouse models and inhibited TNFα-activated intracellular signaling." (PMID 21892962, 2011). "We have demonstrated that TBHsp70 induces IL-10 production by monocytes and synovial cells of arthritis patients, leading to a reduction of TNF-α e IFN-γ levels." (PMID 21170379, 2010). "Apremilast is an orally available PDE4 inhibitor that reduces TNFα production from human synovial cells and significantly suppresses experimental arthritis." (PMID 20525198, 2010). "The selected proteins constitute inflammatory mediators and chemokines involved in arthritis, including TNF-α, IL-17, IL-6, MMP-3 and KC." (PMID 20731827, 2010). "Cells from the prior compartment - in particular, synovial fibroblasts (SFs) - have been identified as the primary targets for TNFα in the development of arthritis." (PMID 20370892, 2010). "Previously, it was demonstrated that TNFR1 in SFs is essential to the development of strictly TNF-driven arthritis." (PMID 20370892, 2010). "Experimental and clinical studies have established prominent roles for TNFα, IL-6 and IL-1 inflammatory pathways in arthritis." (PMID 20497523, 2010). "Many of the expected cytokines are raised during arthritis in this model, such as IL-1β, IL-10 and IL-6, however, unexpectedly both GM-CSF and TNFα remain low." (PMID 21073728, 2010). "It is now clear that some experimental arthritis models are dependent on Th1/IFNγ, whilst others are Th17/IL-17 dependent or switch from TNFα dependency to a Th17/IL-17 profile in later stages of disease." (PMID 20824142, 2010). "It has also been reported that anti-TNFα therapy has little effect on CIA, while anti-TNFα antibodies reduced the severity of inflammation in another arthritis model." (PMID 19296835, 2009). "For example, anti-TNF-α treatment resulted in the reactivation of VL in patients being treated for arthritis, suggesting a protective role of TNF-α against Leishmania infection." (PMID 19468304, 2009).
Arthritis (continued). "We showed that TNF-K immunization is efficacious against established arthritis and induces a transient TNF blockade with reversible effects on arthritis in TTg mice." (PMID 20030816, 2009). "Treatment of TNF-driven Tg197 transgenic mice with PIP-18 significantly modulates disease progression by suppressing arthritis indicators (synovitis, cartilage and bone erosion) as well as circulatory levels of murine sPLA2, IL-6, and human TNF-α." (PMID 19765281, 2009). "Their central importance is demonstrated by the ability of anti-TNFα and anti-IL-1 therapies to markedly reduce clinical and structural measures of disease in arthritic patients and in animals with induced arthritis." (PMID 20003323, 2009). "Western blot analysis indicated that the synovial fluid from joints with LPS-induced arthritis contained TNF-α." (PMID 19916697, 2009). "TNF-α is found in abundance in synovial fluid of patients with arthritis, and the receptors for TNF-α are found on synoviocytes harvested from patient tissue or synovial fluid." (PMID 19695100, 2009). "In GPI-induced arthritis, both TNFα and IL-6 antagonists have protective effects, and these cytokines play important roles in the induction of arthritis in collaboration with autoantibodies (anti-GPI antibodies)." (PMID 19660107, 2009). "Using such a TNFα-dependent arthritis model, we investigated TNFα-related molecules by GeneChip analysis." (PMID 19660107, 2009). "In this regard, we recently demonstrated a clear therapeutic effect of anti-TNF monoclonal antibody (mAb) in mice with GPI-induced arthritis, and the therapeutic response correlated with the in vitro regulation of TNF production." (PMID 19660107, 2009). "Van Maanen and colleagues has recently shown that the use of nicotine and an agonist of the nicotinic acetylcholine receptor subunit α7 reduced severity of clinical signs of arthritis in a CIA model as well as TNFα expression in the murine synovial tissue." (PMID 19519907, 2009). "IL-17A was strongly dependent on TNF-α in the early stages of experimental arthritis; however, at a later stage the disease became IL-17A driven and both TNF-α and IL-1 independent." (PMID 19627579, 2009). "A single injection of 100 μg of anti-TNFα mAb at day 8 ameliorated the disease, as indicated by a rapid fall in the semiquantitative score of arthritis." (PMID 19660107, 2009). "The experimental setup required that the control groups receive the carrier without inflammation-evoking agent, but CFA alone is also able to result in arthritis that is accompanied by increased TNFα expression." (PMID 19296835, 2009). "TNF-α very effectively increases chemokine production in fibroblast-like synoviocytes harvested from arthritis patients." (PMID 19695100, 2009). "Although the therapeutic effect of TNF antagonists is confirmed in RA, only a few animal models of arthritis have been used to confirm the beneficial effects of TNF antagonists." (PMID 19660107, 2009). "While inhibition of IL-1 or TNFα yields significant anti-inflammatory effects in rats with adjuvant-induced arthritis (AIA) and in human arthritis, focal bone erosions in affected joints and systemic bone loss are not fully prevented." (PMID 20003323, 2009). "Triptolide lowers the arthritic scores, delays the onset of collagen induced arthritis and reduces the expressions of TNF-α, IL-6, NF-κB and COX-2 in paw cartilage in arthritic rats." (PMID 19570240, 2009). "Both cytokines have been shown to upregulate catabolic processes in articular cartilage and the IVD that lead directly to matrix degradation, and both TNF-α and IL-1β are thought to be pivotal to the cartilage destruction in arthritis." (PMID 19435506, 2009). "Our previous studies showed that arthritic Lewis (LEW) rats produced the highest levels of tumour necrosis factor (TNF)α in the recovery phase of adjuvant arthritis (AA), suggesting a correlation between high TNFα levels and reduced severity of arthritis." (PMID 18380898, 2008).
Arthritis (continued). "Pre-treatment of LEW rats with TNFα downmodulated the severity of AA, and this TNFα induced protection against arthritis involves suppression of IFN-γ production by the T cells against the arthritogenic epitope of Bhsp65." (PMID 18380898, 2008). "The magnitude of effect of anti-TNF that we observed on the clinical arthritis score is consistent with that reported previously when animals were dosed with the same anti-TNF mAb." (PMID 18234077, 2008). "For example, in the most conventional RA models, such as CIA, treatment with IL-1 antagonists significantly suppressed arthritis, whereas TNF antagonists had minor effect." (PMID 18534002, 2008). "In this regard, we demonstrated a clear therapeutic effect for TNF antagonist in mice with GPI-induced arthritis, and the therapeutic response correlated with the in vitro regulation of TNF production." (PMID 18534002, 2008). "TNF and IL-1β, pivotal cytokines in arthritis pathogenesis, both have the ability to induce the release of HMGB1 from myeloid and dendritic cells." (PMID 18346273, 2008). "To determine the effects of inflammatory cytokines during the effector phase of arthritis, we measured the serum concentrations of TNF-α, IL-6, IL-1β, and IFN-γ at days 0, 7, 14, and 28 in DBA/1 mice after GPI immunization." (PMID 18534002, 2008). "BMP signaling is dynamically activated in collagen-induced arthritis and is partly TNFα-independent." (PMID 18816401, 2008). "Although the therapeutic effect of TNF antagonists has been established in RA, there are few animal models of arthritis in which TNF antagonists are confirmed as being therapeutically beneficial." (PMID 18534002, 2008). "TNFα and high mobility group box chromosomal protein 1 (HMGB1) are two potent proinflammatory cytokines implicated as important mediators of arthritis." (PMID 18582368, 2008). "Patients with psoriatic arthritis and mice with TNF-induced arthritis have increased numbers of circulating OCPs, which correlate with systemically increased TNF concentrations and are reduced by anti-TNF therapy in association with clinical improvement." (PMID 18371213, 2008). "Our results show that pathways other than TNFα are involved in the initiation of joint inflammation in the case of HMGB1-induced arthritis." (PMID 18582368, 2008). "Anti-TNFα drugs have been recently licensed for use in arthritis in a bid to limit the contribution of this cytokine to the chronic joint inflammation." (PMID 18671842, 2008). "The preclinical studies with ISIS 104838 showed it to be effective for the treatment of collagen induced arthritis with activity comparable to that by anti-TNFα antibody, and that it successfully knocks down TNFα expression by 85% in stimulated keratinocytes." (PMID 19787090, 2008). "Lymphatic vessel numbers and size were markedly increased in joint sections of TNF-Tg mice and mice with serum-induced arthritis." (PMID 17997858, 2007). "The role of cytokines like IL-1, IL-6, tumor necrosisfactor-α (TNF-α), prostaglandins (PGs), and nitricoxide (NO) in arthritis has been well established." (PMID 17497032, 2007). "Our findings demonstrated that increased lymphangiogenesis is associated with the progression of joint inflammation, which occurs not only in dysregulated TNF-induced arthritis but also in mice with SIA." (PMID 17997858, 2007). "Our results demonstrate up to 125 fold increases in synovial IL1α and IL1β concentrations, approximately 30 fold increases in levels of IL6 and IL10 and a 200–300 fold elevation in synovial concentrations of TNFα during FCA-induced experimental arthritis." (PMID 17567894, 2007). "Elevated levels of TNF-α andprostaglandins have been reported in arthritic patients and inexperimentally induced arthritis." (PMID 17497032, 2007). "In the murine heat-killed S. aureus-induced arthritis model, TNF-α and IL-1β peaked at 2 and 24 hours after the injection of heat-killed S. aureus, respectively." (PMID 17129374, 2006).